ERCC1 (ERCC excision repair 1, endonuclease non-catalytic subunit)
Diseases named in the same sentence as ERCC1 in open-access papers (continued):
Sharing a sentence is not in itself a finding about the gene and the disease.
cancer (252 papers, 2006 to 2025). A tumor composed of atypical neoplastic, often pleomorphic cells that invade other tissues. "ERCC1-expressing cancer cells have an ability to repair the DNA damage caused by platinum-based drugs and survive." (PMID 40008380, 2025). "In the literature, ERCC1 rs3212986 is also described in association with treatment response, cancer risk, and overall survival and with poor response to chemotherapy and shorter survival time of advanced NSCLC." (PMID 39596349, 2024). "The ERCC1 rs11615 polymorphism was related to the response to platinum and OS, but the correlation is based on specific cancer types in the Asian population." (PMID 37141338, 2023). "In other cancers, the ERCC1 rs11625 wildtype and heterozygotes have been linked with toxicities after oxaliplatin-based chemotherapy, and similar to our findings, improved docetaxel effectiveness has been observed in variant carriers." (PMID 35501422, 2022). "In the past, many literatures have studied the effect of ERCC1 polymorphism on cancers, especially ERCC1 rs3212986 and rs11615." (PMID 36245993, 2022). "The pooled ORs and 95% CIs for the association between ERCC1 rs735482A>C polymorphism and cancer susceptibility." (PMID 35905230, 2022). "The pooled ORs and 95% CIs for the association between ERCC1 rs735482A>C polymorphism and cancer susceptibility of the adjusted OR data." (PMID 35905230, 2022). "The ERCC1 rs735482 is located in the chromosomal region19q13.3, and haplotypes of chromosome 19q13.2–3 have been associated with cancer risk in previous studies." (PMID 35905230, 2022). "Inhibition of HSP90 reduces the expression of senescence-associated inflammatory factors in senescent cancer cells and extends the lifespan of Ercc1-defficient progeroid mice by inducing senescence cell apoptosis." (PMID 34495872, 2021). "The overexpression of ERCC1 is associated with poor response to cisplatin treatment while underexpression is associated with successful cancer control." (PMID 34360968, 2021). "We previously showed that ERCC1 19007 C>T polymorphism was associated with cancer-specific survival (CSS) after platinum-based chemotherapy in patients with advanced urothelial cancer (aUC)." (PMID 34898581, 2021). "It has been reported that the ERCC1 C19007T (rs11615) polymorphism is associated with the response to platinum-based chemotherapy in several types of cancers." (PMID 33029487, 2020). "In general, in all BC subtypes, genes associated with resistance, especially AURKA and ERCC1, were frequently expressed, mostly AT, perhaps representing one of the major problems in cancer treatment." (PMID 32558176, 2020). "ERCC1 polymorphisms have been shown to be associated with the response to chemotherapy in certain cancers." (PMID 33029487, 2020). "Collectively, a meta-analysis of forty-eight publications including 20,993 cases and 26,380 controls explored the contribution of ERCC1 SNPs to cancer susceptibility." (PMID 33266377, 2020). "In view of the previous reports, we chose four SNPs in the ERCC1 gene including rs11615, rs3212948, rs3212961, and rs735482 which are reported to be associated with certain cancers." (PMID 33029487, 2020). "High levels of ERCC1 have been associated with cisplatin resistant cancers, whereas low levels of ERCC1 are found in cisplatin sensitive cancers." (PMID 33102211, 2020). "In view of earlier studies on ERCC1 gene associations with cancer as well as the response to chemotherapy, we chose four ERCC1 SNPs including rs11615, rs3212948, rs3212961, and rs735482 in our study." (PMID 33029487, 2020). "It was previously reported that Ras pathway activation is maintained in the presence of MyD88 and linked to the induction of the DNA repair enzyme ERCC1, enabling efficient DNA repair mechanisms in cancer cells." (PMID 32422978, 2020).
cancer (continued). "In numerous studies, mutation and polymorphism in the hot-spots of the ERCC1 gene in relation to the NER system have been mentioned in other cancers including glioma, cervix, and bladder in different populations." (PMID 31245210, 2019). "Previous studies reported that low ERCC1 expression is associated with clinical benefit in advanced cancer patients receiving platinum-based chemotherapy." (PMID 29781056, 2019). "The C19007T is a common polymorphism of ERCC1 gene and is associated with the effectiveness of platinum-based treatment in several types of cancers." (PMID 28623887, 2017). "The ideal DNA damaging agent to show the effect of targeting ERCC1-XPF activity in cancer cells is short wave UVC irradiation which causes damage that is repaired exclusively by NER." (PMID 28903417, 2017). "This assumption is supported by findings in other cancer types where associations between high ERCC1 expression levels and reduced overall survival had been found." (PMID 28747165, 2017). "While an independently derived ERCC1-XPF interaction inhibitor caused modest enhanced sensitivity to cisplatin in two cancer cell lines and was apparently able, at high concentrations (up to 500 μM), to disrupt the ERCC1-XPF interaction in cell extracts." (PMID 28903417, 2017). "The ERCC1 mRNA and protein expressions are associated with the effectiveness of platinum-based chemotherapy in several cancers." (PMID 28623887, 2017). "Several studies have previously reported an association with the ERCC1 promoter SNP rs2298881 and cancer risk." (PMID 26967386, 2016). "Genetic polymorphism of ERCC1 has also been investigated for the association with the risk and clinical outcome of many types of cancer including NSCLC." (PMID 26056042, 2015). "Genetic polymorphisms of ERCC1 have been investigated in terms of the risk and the clinical outcomes in many types of cancer including NSCLC." (PMID 26056042, 2015). "We examined the association of ERCC1 and TS expression with OS in TCGA pan-cancer and mCRC cohorts to see if the observed trends would generalize to these independent cohorts." (PMID 26083491, 2015). "High ERCC1 expression has been demonstrated to be associated with resistance to platinum-based chemotherapy and worse prognosis in cancer patients." (PMID 25253066, 2014). "Because low DNA repair capacity leads to higher genomic instability, and consequently higher cancer susceptibility and improved response to DNA-damaging treatment, the ERCC1 8092Ala allele probably has higher DRC than the 8092Cys allele in NPC." (PMID 25025378, 2014). "Increased expression of ERCC1 in several cancers has been associated with more efficient removal of DNA adducts induced by platinum, leading to clinical resistance to cisplatin-based chemotherapy." (PMID 23299493, 2013). "Certain polymorphisms in ERCC1 have been described to be associated with cisplatin sensitivity in multiple types of cancer." (PMID 23613873, 2013). "Previous reports on the association between ERCC1 rs3212986 and cancer survival have been controversial." (PMID 24023723, 2013). "Previous studies have found that over expression of ERCC1 is associated with resistance to cisplatin-based chemotherapy in various cancers, including NPC." (PMID 24340057, 2013). "ERCC-1 is a key enzyme in nucleotide excision repair and mutations in this gene appear to play a role in cancer pathogenesis." (PMID 22890830, 2012). "Clearly, the relationship between ethanol consumption, Ercc1 expression, brain volume, neuropsychological function, aging, and cancer risk merits further investigation." (PMID 23095216, 2012). "Multivariate analysis revealed that low expression of ERCC1 to be an independent factor associated with a lower risk of cancer death (HR 0.31, p = 0.010)." (PMID 21426588, 2011).
cancer (continued). "Although these studies have shown possible relationship between ERCC1 polymorphism and effectiveness of cancer treatment or survival of cancer patients, the biological effect of this synonymous SNP is unclear." (PMID 20003463, 2009). "Individuals carrying ERCC1 118TT homozygote genotype had a 2.01-fold (marginally significant) increased risk of cancer compared with the wild genotype (95%CI 0.99-4.10, P = 0.054)." (PMID 20003391, 2009). "Multivariate analysis revealed that low expression of ERCC1 was an independent factor associated with a lower risk of cancer death (HR 0.12, P=0.043)." (PMID 18594541, 2008). "Given its role in repairing DNA crosslinks, any deficiencies in ERCC1 could increase the cancer cells’ sensitivity to DNA-damaging agents but also raise the risk of resistance through alternative repair mechanisms." (PMID 39925800, 2025). "The association between ERCC1 rs11615 and cancer risk differs according to the cancer type." (PMID 35637613, 2023). "Interestingly, the ERCC1 codon 118 C/T polymorphism was strongly associated with distant metastasis (p ≤ 0.001) and cancer resistance (p ≤ 0.001)." (PMID 37510370, 2023). "All these results strongly support a possible role of ERCC1 in cancer risk." (PMID 35905230, 2022). "Stratified analysis of ERCC1 rs735482A>C variant on cancer susceptibility." (PMID 35905230, 2022). "Nevertheless, more studies have focused on the association between ERCC1 rs11615 and cancer." (PMID 36245993, 2022). "Expression of ERCC1 is associated with chemoresistance in many cancers." (PMID 36335317, 2022). "However, the ERCC1 rs735482 is associated with a decreased risk of cancer in Italian group (AB vs AA, OR = 0.600, 95% CI = 0.402–0.859, P = .012; AB + BB vs AA, OR = 0.620, 95% CI = 0.424–0.908, P = .014)." (PMID 35905230, 2022). "In addition, homozygote ERCC1 C118T (rs11615) variants were associated with lung and smoking-related cancer incidence." (PMID 33266377, 2020). "On the basis of these study results, we speculate that the CC genotypes of ERCC5 rs17655 and ERCC1 rs735482 may increase the DNA-repair capacity of cancer cells, leading to increased susceptibility to recurrence." (PMID 30609649, 2019). "77% of CRC patients with cancer-associated variants had the ERCC1 c.354T > C variant." (PMID 30850667, 2019). "The higher percentage of ERCC1 variant in CRC patients with pathogenic variants of cancer-associated genes might explain the better survival in this group of patients." (PMID 30850667, 2019). "The over-expression of ERCC1, an essential endonuclease of this pathway, has been associated with cellular resistance to platinum-based chemotherapy in different cancers suggesting that platinum-based chemotherapy would be more effective in ERCC1-negative cancers." (PMID 30718758, 2019). "Other studies have also clearly shown a positive association of higher ERCC1 expression with the DNA repair ability in cancer patients that might possibly be one of the explanations of resistance to platinum-based treatments." (PMID 30718758, 2019). "Mutations in this gene contributed to the etiology of cerebro-oculo-facio-skeletal (COFS) syndrome, and polymorphisms in ERCC1 that alter its expression may influence overall genomic stability, and thus enhance personal susceptibility to cancer." (PMID 30096175, 2018). "The rs11615, one of the common polymorphisms in ERCC1, may decrease the expression of ERCC1 mRNA, thus reducing the resistance to chemotherapy for cancer patients." (PMID 28388903, 2017). "Moreover, the single nucleotide polymorphisms (SNPs) of ERCC1 are considered as potential predictive biomarkers for many different types of cancers." (PMID 28623887, 2017). "In addition, the PPP1R13L, CD3EAP and ERCC1 polymorphisms are in linkage disequilibrium with each other in cancers, and XPC rs2228001 and rs2279017 and XPF rs4781560, which are located in the same region, had significant linkage disequilibrium." (PMID 26681190, 2015).
cancer (continued). "Therefore, ERCC1 has been linked to protection against development and progression of cancer, and resistance to platinum-based anticancer drugs at the same time: the double-edged sword." (PMID 26056042, 2015). "Overall, aberrant expression of ERCC1 appears to be associated with cancer risk." (PMID 25780441, 2015). "Meta-analysis suggests that certain ERCC1 SNPs may also be predictive of cancer susceptibility, further highlighting potential importance of this genetic alteration in cancer detection and therapeutics." (PMID 25191856, 2014). "Therefore, potential associations between ERCC1 gene polymorphisms and cancer risk have evoked great interest." (PMID 24841208, 2014). "Functional genetic variations in the ERCC1 gene may alter DNA repair capacity and modulate cancer risk." (PMID 24841208, 2014). "ERCC1, which is involved in nucleotide excision repair and associated with resistance to cisplatin-based chemotherapy or chemoradiotherapy in various types of cancer." (PMID 23259415, 2012). "Further examination could reveal that ERCC1, 2, 3, 4, and 8 expressions were significantly higher in the C4 and 5 subtype compared to the other subtypes, implying a potential association between these genes and the promotion of cancer." (PMID 39192988, 2024). "Based on this hypothesis, we searched the literatures and found that the correlation between ERCC1 rs11615 polymorphism and susceptibility to cancers has been reported in multiple meta-analyses, such as breast cancer, lung cancer, pancreatic cancer, head-and-neck cancer, and colorectal cancer." (PMID 36245993, 2022). "The possible mechanism of the expression of ERCC1 on radiotherapy sensitivity could be due to the fact that radiation could cause double-strand breaks and single-strand breaks in cellular DNA through free radicals to limit the progression of cancer." (PMID 36230725, 2022). "ERCC1 status represents both the cellular intrinsic DNA damage repair ability and the extent of accumulated intratumoral DNA damage, which may be associated with the progression of the cancers." (PMID 36713431, 2022). "Furthermore, for patients with HRD, PARPi used in the populations of ERCC1 or BRCA deficient cancers, might potentiate their therapeutic effects by regulating the signal pathway related to antitumor immunity." (PMID 33705352, 2021). "Moreover, high expression of ERCC1 has been associated with poor response to chemotherapy in many cancers and could be a potential target to overcome resistance." (PMID 28292785, 2017). "However, while ERCC1 may predict chemotherapy sensitivity in these cancers, low ERCC1 expression was also associated with higher tumorigenesis risk." (PMID 28977987, 2017). "Sequence variations in ERCC1 gene may indeed alter the DNA repair capacity, making biologically plausible to assume that polymorphisms of this gene might have functional significance in cancer." (PMID 25253066, 2014). "Thus, functional polymorphisms in the ERCC1 gene that compromise DNA repair capacity may be a potential risk factor for tobacco-induced cancers." (PMID 24841208, 2014). "Previous studies have demonstrated that the excision repair cross complementation group 1 (ERCC1) protein can successfully augur the response to chemotherapy in cancer; however, data related to TNBCs, particularly in Pakistan, are limited." (PMID 40008380, 2025). "We found that, similar to PRMTs, ERCC1 expression was significantly upregulated across cancer samples compared with their corresponding control specimens." (PMID 38826355, 2025). "More importantly, the combination treatment almost completely repressed ERCC1 protein expression in cancer cell lines." (PMID 38826355, 2025). "Several studies have shown a significant correlation between low ERCC1 expression and both higher response rates to CT and better clinical outcomes in cancer patients." (PMID 39735668, 2025). "Colony formation assays demonstrated that ERCC1 knockout cancer cell lines were sensitized to PARPi treatments." (PMID 38826355, 2025).
cancer (continued). "To further demonstrate the functional involvement of ERCC1 in the synergistic actions between PRMTis and PARPi, we knocked out ERCC1 in cancer cell lines using CRISPR/Cas9." (PMID 38826355, 2025). "Further studies are needed to fully understand the connection between ERCC1 and ERCC2 deficiencies and cancer risk, as well as to explore potential therapeutic strategies for individuals with these deficiencies." (PMID 39834980, 2024). "Deficiency in ERCC1 and ERCC2 can lead to a higher accumulation of DNA damage, which increases the likelihood of mutations that can ultimately lead to cancer development." (PMID 39834980, 2024). "For instance, ERCC1 demonstrated increased expression in cancerous tissues across all examined cancer types, surpassing its expression levels in normal tissues." (PMID 39192988, 2024). "Targeting the ERCC1/XPF dimerization brings forth a strategy to augment chemotherapy by eschewing the resistance mechanism integral to cancer cells." (PMID 39051064, 2024). "Cells defective in ERCC1 and XPF genes were 100‐fold more sensitive to cisplatin than the parental line, as well as cancer cells where the complex ERCC1‐XPF has been silenced." (PMID 39492835, 2024). "In metastatic or high ERCC1 expressing cancer cells, downregulation of ERCC1 reversed chemoresistance against oxaliplatin or cisplatin." (PMID 38272916, 2024). "ERCC1 has been put forward and tested extensively to predict platinum response in cancer therapy, with occasionally positive results." (PMID 38272916, 2024). "IHC analysis revealed that cytoplasmic ERCC1 staining was significantly and inversely related to distant metastasis (p = 0.038) and cancer recurrence (p = 0.05)." (PMID 37510370, 2023). "Suppressing the function of ERCC1–XPF is very important to increase the effectiveness of chemotherapy and radiotherapy in cancer because both chemotherapy and radiotherapy cause cancer cell death through DNA damage, DNA cross-link, and DNA break." (PMID 37296596, 2023). "In line with previous publications showing TGFb inhibition disrupts DNA repair processes in cancer cells and HSCs, these four inhibitors also disrupted several DNA repair proceses in our Ercc1 FBs." (PMID 38322248, 2023). "ERCC1 methylation was observed in 40% of early-stage cancers compared to 47% in the advanced cancer stages." (PMID 37510370, 2023). "As a highly conserved enzyme, ERCC1 participates in the key steps of nucleotide excision repair, and its expression level is a major predictor of cancer response to platinum‐based chemotherapy." (PMID 37400750, 2023). "Based on current observations, tumors harbouring a combined methylation of MGMT and ERCC1 had a strong tendency towards lymph node metastasis, distant spread, perineural invasion, cancer relapse, and overall survival." (PMID 37510370, 2023). "EGCG enhanced the sensitivity of cancer cells to cisplatin via targeting ERCC1/XPF, leading to the inhibition of DNA repair of the cancer cells." (PMID 36545470, 2022). "Results show that doxycycline treatment at 50 mg/kg was capable of regulating ERCC1 overexpression in vivo, thus confirming the successful establishment of an animal model for precise ectopic cancer ERCC1 regulation." (PMID 36230725, 2022). "HCT116-Tet-on and COLO205-Tet-on heterotopic cancer animal models were established to verify the induction of ERCC1 expression in tumors via in vivo injection of doxycycline." (PMID 36230725, 2022). "Cancer cells treated with cisplatin resulted in a significant elevation of ERCC1 expression, while a cisplatin-resistant cell line HCA-1R presented with a dramatically higher level of ERCC1 mRNA expression than the native cells." (PMID 36713431, 2022).